ILK (integrin linked kinase)
Diseases named in the same sentence as ILK in open-access papers (continued):
Sharing a sentence is not in itself a finding about the gene and the disease.
colon carcinoma (25 papers, 2003 to 2024). "Integrin-linked kinase (ILK) promotes colon inflammation and tumorigenesis and can be used as a biomarker for colon cancer prognosis and immune cell invasion." (PMID 37020597, 2023). "The impact of myeloid-ILK deficiency on colon tumour development suggests a macrophage-intrinsic role of ILK affecting tumour growth via the regulation of macrophage phenotypes." (PMID 38077324, 2023). "Our data are in line with recent findings demonstrating that inhibition of integrin-linked kinase activity in breast, prostate and colon cancer cells activated the Hippo pathway." (PMID 27409827, 2016). "Overexpression of Tβ4 in human colon cancer cells may induce epithelial–mesenchymal transition (EMT) by upregulating recombinant integrin-linked kinase (ILK)." (PMID 38256161, 2024). "We show that myeloid-ILK deficiency decreases both AOM/DSS-induced and APCmin/+-driven colon tumour burden." (PMID 38077324, 2023). "More recent evidence from studies on patients and chemoresistant colon cancers further evaluated the correlation of ILK expression and the level of a wide range of EMT markers." (PMID 35089438, 2022). "The GSE10950 dataset showed that CDKN2A and CMTM8 mRNA expression levels were up-regulated in colon cancer samples, while ILK was considerably down-regulated in colon cancer samples." (PMID 35429970, 2022). "We performed experiments in detecting protein expression of CDKN2A, CMTM8 and ILK by immunohistochemistry in the colon cancer tissues and adjacent tissues." (PMID 35429970, 2022). "While this suggested that ILK plays an important role in the inflammatory tumor microenvironment in colon cancer, mechanisms involved remain to be established." (PMID 35692780, 2022). "Our results are consistent with these studies as we found that ILK is significantly correlated with advanced Duke’s stages of colon cancer which are accompanied by invasion and metastasis and ILK expression is also correlated with EMT gene marker expression." (PMID 35692780, 2022). "To sum up, we found that CDKN2A and CMTM8 were up-regulated in colon cancer, while, ILK was down-regulated." (PMID 35429970, 2022). "ILK is expressed in different cell types in colon cancer including epithelial cancer, stromal and immune cells." (PMID 35692780, 2022). "That is confirmed in cells from colon cancer via immune cell atlas platform as found that ILK is expressed in stromal cells, myeloid cells and TNKILC, and ILK expression in these cell types is higher than its expression in epithelial cancer cells." (PMID 35692780, 2022). "When Tβ4 is overexpressed in colon carcinoma cells, EMT occurs with downregulation of E-cadherin by ZEB1-mediation transcriptional repression and an accumulation of β-catenin, mediated by integrin-linked kinase (ILK) and Akt." (PMID 33948525, 2021). "Although there are few studies in colon cancer showing direct angiogenesis induction by ILK, one report has revealed that ILK overexpression regulates mesenchymal stem cell survival and angiogenesis via Akt and mTOR phosphorylation and VEGF expression." (PMID 34163519, 2021). "Like our results, it has been reported that ILK is a key molecule in the progression of human colon cancer, possibly by in vivo regulation of β-catenin, E-cadherin, and AKT pathways." (PMID 35317111, 2021). "On the contrary, an unchanged level of Akt phosphorylation at Thr 308 was reported, when the ILK expression was silenced in colon cancer cells." (PMID 34359835, 2021). "The overexpression of ILK was reported to increase gene transcription of Snail in human colon carcinoma cells." (PMID 25821081, 2015). "Overexpression of ILK was previously shown to increase fibronectin deposition in rat intestinal cells while ILK knockdown decreases fibronectin expression in mice and human colon cancer cells." (PMID 22988499, 2012).
colon carcinoma (continued). "ILK has also been shown to have implication in colon cancer progression that higher ILK expression was detected in metastatic tumor and was increased with tumor stage, grade and invasiveness." (PMID 21347395, 2011). "Based upon these results, it appears that changes in the expression of ILK occur prior to changes in the metastatic potential of colon cancer cells." (PMID 12771992, 2003). "In summary, we suggest that dysregulation of ILK signalling is an important early event in the genesis of human colon cancer." (PMID 12771992, 2003). "Based upon our findings, we conclude that dysregulation of the ILK-signalling nexus is an important early event in the genesis of human colon cancer." (PMID 12771992, 2003). "In the present study, we report for the first time that the expression of ILK is significantly increased in sporadic colon cancer and metastatic deposits in regional lymph nodes, thus substantiating our original findings in colonic polyposis." (PMID 12771992, 2003). "In this study, we extended our previous work by investigating the ILK-signalling pathway in sporadic human colon cancer and representative lymph node metastases." (PMID 12771992, 2003). "Based on these observations, we investigated further whether myeloid-ILK plays a role in colitis- independent colon tumour development." (PMID 38077324, 2023). "In order to examine the association of ILK expression with stages of colon cancer, the data from the GENT2 platform were utilized and gene expression of ILK investigated in different Duke’s stages of 290 colon cancer patients." (PMID 35692780, 2022). "So, CDKN2A, CMTM8 and ILK may affect the prognosis of colon cancer by influencing EMT and immune simultaneously." (PMID 35429970, 2022). "Combined with our results, it can be inferred that the up-regulated CDKN2A, CMTM8, and down-regulated ILK may aggravate the progression of EMT by the TGF-β pathway in colon cancer, as a result, promoting the infiltration and metastasis." (PMID 35429970, 2022). "Moreover, CAFs are involved in EMT induction to facilitate invasion and metastasis, and ILK has been shown to induce EMT in colon cancer." (PMID 35692780, 2022). "CDKN2A, CMTM8 and ILK are promising prognostic biomarkers and may be potential therapeutic targets in colon cancer." (PMID 35429970, 2022). "We found that ILK is down-regulated in colon cancer and leads to a poor prognosis." (PMID 35429970, 2022). "Collectively, these results indicate a potential role for ILK in colon cancer prognosis." (PMID 35692780, 2022). "Furthermore, a study has reported that the Akt-mTOR signaling pathway which is known to be regulated by ILK is also involved in angiogenesis in colon cancer." (PMID 34163519, 2021). "Also, ILK inhibition in colon cancer cells reduces tumor growth in mouse models and in vitro cell lines via reducing β-catenin nuclear expression and increasing GSK3β activity by phosphorylation reduction, resulting in β-catenin degradation." (PMID 34163519, 2021). "For example, in contrast to the previous report that ILK increased transcription of the Snail gene in human colon carcinoma cells, the present study indicates that ILK promoted the upregulation of Snail via multiple pathways involving HIF-1α, YB-1, and GSK3β at different cellular levels." (PMID 25821081, 2015). "To determine whether ILK was also dysregulated in sporadic cases of human colon cancer, we examined both the protein expression of ILK by immunohistochemical analysis and the mRNA levels using microarray technology." (PMID 12771992, 2003). "As well, we are attempting to unravel the mechanism by which ILK is dysregulated in colon cancer." (PMID 12771992, 2003). "Based upon the presented data, we propose that ILK signalling is dysregulated early during the development of human colon cancer, and that selective inhibition of this molecule alone or in combination with the standard therapeutic modality might be a more effective means of treating colon cancer." (PMID 12771992, 2003).
colon carcinoma (continued). "To determine whether ILK activity was similarly affected in human colon cancer, we characterised the biochemical activity in a total of 38 cases (16 cases in which metastatic deposits were present in the regional lymph nodes; an additional 22 cases with no lymphatic invasion)." (PMID 12771992, 2003). "We also observed that ILK is highly expressed in the TME because its expression in stromal and immune cells, in addition to the epithelial cancer cells in colon cancer." (PMID 35692780, 2022). "Although there are insufficient studies linking ILK and MAPK (p38, Erk1/2, and JNK) signaling in colon cancer, some studies have demonstrated such an interaction in different cell types." (PMID 34163519, 2021). "We recently reported that ILK signalling was also dysregulated in patients with the genetic condition familial adenomatous polyposis (FAP), a precursor to colon cancer." (PMID 12771992, 2003). "Increased levels of ILK expression results in upregulation of EMT markers including Snail, Slug, vimentin, and N-cadherin, and suppression of E-cadherin expression, promoting EMT, invasion, and metastasis in oral, lung, and colon cancer." (PMID 35804980, 2022). "The most recent study showed that treatment with a small molecule inhibitor of ILK, QLT0267, may reduce acquired resistance to 5-fluorouracil of human colon cancer cells." (PMID 35089438, 2022).
glioma (25 papers, 2010 to 2025). A benign or malignant brain and spinal cord tumor that arises from glial cells (astrocytes, oligodendrocytes, ependymal cells). "Using the same NPE glioma model used in the current study, we recently reported on another integrin adhesome node, namely, integrin-linked kinase (ILK), which controls transcriptional plasticity." (PMID 40430842, 2025). "In case of GBM, IGFBP2 binds specifically with β1 integrin in order to activate an integrin-linked kinase (ILK)/NF-κB cascade that further mediates the growth of glioma." (PMID 34512336, 2021). "Sylvie M also reported that ανβ3 and ανβ5 regulate mitotic cell death via ILK (integrin-linked kinase) and RhoB signaling pathways, which participate in the radioresistance of glioma cells." (PMID 23755149, 2014). "Combination therapies are sought to develop alternative therapeutic strategies for a wide variety of solid tumours, such as gliomas in situations where there is resistance to ABL or ILK inhibitors alone." (PMID 37508338, 2023). "Recent research demonstrated that IGFBP2 activates integrin β1 pathways, recruits ILK for cell migration, and activates NF-κB in glioma." (PMID 37957694, 2023). "QLT0276 in DMSO inhibits integrin-linked kinase (ILK), leading to decreased glioma cell invasiveness and down-regulated proliferation and invasion." (PMID 38002561, 2023). "In gliomas, IGFBP2 is considered to be an oncogene that causes glioma progression through integrin/ILK/NF-kB pathway." (PMID 32296458, 2020). "Glioma-associated DEGs DOCK6, ILK, MGMT, NOTCH4 were up-regulated and FGF10, JAK1, JUNB, RHOB were down-regulated uniquely in the mouse." (PMID 29352201, 2018). "Like leukemic stem cells, our study indicates that combination therapies that target ABL and ILK in glioblastoma may optimize therapeutic benefits for these drug-resistant and aggressive CNS cancers." (PMID 37508338, 2023). "In glioma, ILK promotes cancer cell migration and aggressiveness via activating ROCK1 and fascin-1." (PMID 35029589, 2022). "ILK interacts with Rictor to mediate Akt-S473 phosphorylation in different cell types and Rictor may interact with Tspan8 in glioma cells." (PMID 28188308, 2017). "Indeed, the IGFBP2/integrin/ILK/NF-kB network was recently reported to be a key player in glioma progression and poor outcomes." (PMID 24069370, 2013). "The top five pathways that MTORT1 is possibly involved in are Production of Nitric Oxide and Reactive Oxygen Species in Macrophages, Gq Signaling, Glioma Invasiveness Signaling, FGF Signaling, and ILK Signaling." (PMID 34141617, 2021). "Recent studies in glioma implicate IGFBP2 in the activation of PI3K Akt pathway, integrin/ILK/NF-B network which drives glioma progression in mice and binding to integrin α5 that brings about increased migration and invasion." (PMID 23767917, 2013). "Nevertheless, it has been shown that intrinsic IGFBP2 interacts with integrin α5β1 and promotes migration of glioma cells and glioma progression through activation of AKT, ILK, and NF-κB pathways." (PMID 24191913, 2013). "Furthermore, they found that suppression of SPARC expression with specific siRNAs in glioma cells decreased tumor cell survival upon the downregulation of FAK and/or ILK expression." (PMID 31897236, 2020). "In addition, suppression of SPARC expression decreases Akt, ILK and FAK activation, and SHC/RAF/ERK signaling is also involved in SPARC-mediated invasiveness in glioma." (PMID 28969021, 2017). "The data show that pFAK and pSrc expression was reduced 24–96 h upon TMZ treatment (following 48 h β3-siRNA transfection), while the expression of ILK was not changed (data not shown), indicating that integrin αVβ3 signals in glioma cells through pFAK and pSrc." (PMID 27487141, 2017).
lung carcinoma (23 papers, 2003 to 2023). "In the H661 lung cancer cell line, lunasin prevented β1 and β3 subunits from interacting with pFAK, integrin-linked protein kinase (ILK), and kindlin, while further blocking FAK, Akt, and ERK1/2 phosphorylation." (PMID 36076946, 2022). "For lung cancer, the integrin-linked kinase signaling pathway was selected as significant in the two groups." (PMID 29247873, 2017). "ILK expression and activity have been revealed to be increased in association with tumor grade, T status, lymph node metastasis and survival in lung cancer patients." (PMID 25760437, 2015). "Additionally, shear stress can increase the CSC phenotype of lung cancer cells, and matrix stiffness promotes the development of breast CSCs via modulation of integrin-linked kinase (ILK)." (PMID 31185668, 2019). "In addition, other studies showcased that some downregulated tsRNAs were involved in the chemoresistance of lung cancer cells via integrin-linked kinase (ILK) signalling, phosphatase and tensin homolog (PTEN) signalling, and other pathways involved in the regulation of chemo-resistance." (PMID 35574338, 2022). "When compared with lung cancer cell lines, the human hepatoma cell line HepG2 differed in its response to treatment with Si135 and included upregulated insulin-like growth factor (Igf) and integrin-linked kinase (Ilk) that are reported to be induced in hepatocellular carcinoma." (PMID 21152443, 2010). "Prior study also found that PARVA plays a critical role in promoting lung cancer by regulating ILK pathway." (PMID 37228122, 2023). "Pharmacologic inhibition of ILK in KRAS-mutant lung cancer cells increases sensitivity to platinum-based chemotherapy." (PMID 35804980, 2022). "Corroborating those results it was shown that RNA silencing of ILK expression increased the sensitivity of the lung cancer cells to cisplatin, enhancing its apoptotic action." (PMID 35089438, 2022). "There is a particularly close relationship between ILK-mediated signaling and sensitivity to platinum-based chemotherapeutics such as cisplatin, especially in ovarian and lung cancer." (PMID 35804980, 2022). "ILK has been demonstrated to promote lung cancer cell migration and invasion through the induction of the EMT process." (PMID 35089438, 2022). "The modulatory properties of this substance are provided by decreasing the expression of cellular integrins β1, β4, integrin-linked kinase (ILK), and focal adhesion kinase (FAK) pathways, as well as β-catenin in lung cancer cells." (PMID 34577581, 2021). "Studies have shown that FN binding to tumor cell membrane integrins can activate downstream signaling pathways such as the integrin-linked kinase (ILK) and NF-κΒ pathways, thereby regulating the expression of EMT-related genes in lung cancer." (PMID 31886230, 2019). "First, we found by immunoprecipitation assays that PARVA interacted with ILK in CL1–0 lung cancer cells." (PMID 25738875, 2015). "In conclusion, the results from the present study have identified for the first time, to the best of our knowledge, that downregulating ILK expression inhibits proliferation and cell cycle arrest in lung cancer cells." (PMID 25760437, 2015). "ILK promotes lung cancer cell migration and invasion via upregulation of matrix metal-loproteinase-9 (MMP-9) and epithelial-mesenchymal transition-associated genes, including vimentin, fibronectin, Snail and Slug." (PMID 25760437, 2015). "Here we showed that rVP1 inhibited lung cancer invasion by decreasing FAK/PI3K/PIP3 to downregulate ILK and phospho-AktS473 in the lipid rafts." (PMID 25004182, 2014). "As MUC1-C has been reported to confer KRAS independence in mutant KRAS lung cancer cells, it warrants investigation whether targeting ILK can mitigate the effect of MUC1-C overexpression on KRAS independence." (PMID 28692035, 2017).